GAST (gastrin)
Diseases named in the same sentence as GAST in open-access papers (continued):
Sharing a sentence is not in itself a finding about the gene and the disease.
gastrinoma (85 papers, 2005 to 2026). "Zollinger–Ellison syndrome (ZES) is a rare but clinically significant disorder characterized by gastrin‐secreting neuroendocrine tumors (gastrinomas) that cause pathological gastric acid hypersecretion." (PMID 41585576, 2026). "Zollinger–Ellison syndrome (ZES) is caused by gastrin secretion by duodenal or pancreatic neuroendocrine tumors (gastrinomas)." (PMID 40941664, 2025). "Approximately 30% of pNETs are gastrinomas, which due to the excess of secreted gastrin cause peptic ulcers (sdr Zollinger-Ellison)." (PMID 39941198, 2025). "A case report describing that the removal of all gastrinomas in a patient with MEN1 caused the gastric NETs to disappear showed that gastrin is the dominating cause of these tumors also in this condition." (PMID 37686307, 2023). "Zollinger-Ellison syndrome (ZES) is a rare condition caused by gastrin-secreting neuroendocrine tumors known as gastrinomas." (PMID 37700944, 2023). "Gastrinomas are usually located in the duodenum or pancreas, secrete gastrin, and cause a clinical syndrome known as ZES." (PMID 36950054, 2023). "Gastrinomas have calcium channels; therefore, a high extracellular calcium concentration causes degranulation of the gastrinoma cells and subsequent release of gastrin." (PMID 33206240, 2020). "ZES, a common presentation of most gastrinomas, was first reported in 1955, and is caused by malignant gastrin-producing neuroendocrine tumors." (PMID 33206240, 2020). "Type II lesions are caused by gastrinomas (gastrin-producing tumors), also known as Zollinger-Ellison syndrome." (PMID 29257854, 2017). "Mostly, it is a secondary disease caused by a tumor in pancreas (gastrinoma), duodenum or abdominal lymph nodes which causes increased secretion of gastrin." (PMID 26870134, 2015). "Gastrinomas causes severe, unopposed gastrin elevations (>2000 pg/ml, although it can have a wide range of 300–2000 pg/ml)." (PMID 25698559, 2015). "In the presence of gastrinoma, gastrin production is increased by the tumor which causes increased secretion of HCl." (PMID 26870134, 2015). "To summarize, MEN-1 associated duodenal gastrinomas are preceded by gastrin-positive cell hyperplasia." (PMID 24213225, 2012). "Gastrinoma is characterized byelevated basal serum concentration of gastrin, a hormone causing gastric acid hypersecretion." (PMID 23487241, 2011). "ZES is a clinical syndrome caused by excessive gastrin secretion from gastrinoma." (PMID 40291307, 2025). "Gastrinomas secrete gastrin and cause Zollinger–Ellison syndrome (ZES)." (PMID 37623030, 2023). "The diagnosis of gastrinomas is based on the presence of Zollinger-Ellison syndrome, which is characterised by the association of severe peptic ulceration and profuse volumogenic diarrhoea that is related to the hypersecretion of gastrin." (PMID 32947997, 2020). "In MEN1, duodenal gastrinomas are usually multiple, smaller than 5 mm in diameter, associated to foci of gastrin-positive cells, and with a predominance in the proximal duodenum, while the pancreatic counterpart is usually single and greater than 1 cm in diameter." (PMID 24213321, 2012). "As the next step in the tumorigenesis of MEN-1 associated gastrinomas micro-invasive lesions, small clusters of gastrin-positive cells in the lamina propria between the glands, resulting in micro-tumours (>250 μm) with trabecular growth pattern and fibrosis have been described." (PMID 24213225, 2012). "Zollinger-Ellison syndrome is caused by gastrin-secreting tumors called gastrinomas." (PMID 16042772, 2005). "However, the diagnostic performance of the serum gastrin assay in dogs with gastrinoma cannot be determined as the overall prevalence of the condition in dogs is unknown." (PMID 29115998, 2017). "Several reports noted the adjunctive use of somatostatin analogs (octreotide) to curb gastrin secretion, and in select patients, surgical resection of the gastrinoma was performed after recovery from perforation." (PMID 41585576, 2026).
gastrinoma (continued). "Long‐term care must include endocrine follow‐up, biochemical surveillance of gastrin levels, and assessment for recurrent or metastatic gastrinoma." (PMID 41585576, 2026). "In a typical patient, the fasting gastrin levels are less than 100 pg/ml; however, a suspicion for gastrinoma is higher if the fasting gastrin levels are greater than 300 pg/ml." (PMID 40291307, 2025). "Classic examples of circulating biomarkers include CgA or NsE, and hormones associated with hormone-secreting syndromes (e.g., insulin for insulinomas, gastrin for gastrinomas, and metanephrines in PPGLs)." (PMID 40038821, 2025). "Current diagnosis of these neoplasms relies on tissue biopsies and biochemical analyses, that can be general or specific for certain NENs such as gastrin for gastrinomas, coupled to imaging techniques." (PMID 40038821, 2025). "Fasting serum gastrin level is a valuable screening test in patients with unexplained chronic diarrhea to evaluate for gastrinoma." (PMID 40291307, 2025). "In a subset of metastatic gastrinoma patients treated with 90Y and/or 177Lu-based therapies, studies reported reductions in serum gastrin levels by up to 81%, along with tumor response in over 50% of cases." (PMID 40647278, 2025). "Gastrin-producing tumors are the most common duodenal NETs, and most of these are monohormonal, with diffuse positivity that allows them to be classified as G cell tumors." (PMID 40553402, 2025). "Type 2 g-NETs, which account for 5% to 7% of cases, result from excessive gastrin secretion due to gastrinomas." (PMID 41426335, 2025). "In view of multiple ulcers in unusual locations and oesophagitis being resistant to treatment, gastrinoma was suspected, and serum gastrin levels were sent, which were found to be 696 pg/mL." (PMID 40291307, 2025). "It is currently suggested to perform annual screening for insulinoma by fasting glucose starting at the age of 5 years and for gastrinoma by fasting serum gastrin (FSG) levels starting at the age 20 years." (PMID 38893191, 2024). "In cases of concomitant pHPT, parathyroidectomy precedes treatment for gastrinoma as elevated calcium levels stimulate gastrin secretion." (PMID 38893191, 2024). "Type-2 G-NETs are the least common subtype (5-10%) and usually occur in response to gastrinomas (gastrin-producing tumors), also termed Zollinger Ellison Syndrome (ZES), associated with MEN1." (PMID 39669826, 2024). "Diagnosis of gastrinoma should be made when plasma gastrin levels peak within 10 min after glucagon administration, with an increase of greater than 200 pg/mL and greater than 35% of the basal value." (PMID 38928704, 2024). "Type 2 G-NETs share the same pathological pathway due to excessive production of gastrin, although they are produced by a gastrinoma in the context of Zollinger–Ellison syndrome, usually in the setting of a multiple endocrine neoplasia type 1 (MEN-1)." (PMID 38254841, 2024). "SASI is an angiographic test similar to ASVS used for insulinomas in which secretin is injected into the feeding vessels supplying the gastrinoma and gastrin levels are measured in the hepatic vein at 20, 40, 60, 90, and 120 s post injection." (PMID 38672582, 2024). "GEP-NETs that secrete the gastric peptide hormone gastrin (i.e., gastrinoma) comprise the most clinically aggressive of MEN1 cases, with 60% of patients presenting with lymph node metastases upon diagnosis." (PMID 37492626, 2023). "In functional tumors, measurement of specific hormones is appropriate [glucagon in glucagonoma, vasoactive intestinal peptide (VIP) in VIPoma, gastrin in gastrinoma, insulin in insulinoma, etc.]." (PMID 36950054, 2023). "Gastrinoma is characterized by uncontrolled gastrin secretion which leads to overproduction of gastric acid from G cells, thereby causing Zollinger–Ellison syndrome, the second most common hormonal syndrome associated with functioning PanNENs." (PMID 36830839, 2023).
gastrinoma (continued). "We present a case report where a patient was diagnosed with gastrinoma with relatively low serum gastrin levels after subsequent duodenojejunostomy, gastrojejunostomy, total gastrectomy, and cholecystectomy." (PMID 37575785, 2023). "During the test, secretin normally has an inhibitory effect on gastrin release; however, in gastrinoma patients, it will increase gastrin release." (PMID 37568540, 2023). "Calcium-sensing receptors (CaRs) are expressed on gastrinomas and mediate calcium-stimulated gastrin release." (PMID 37568540, 2023). "Most of the removed metastases involved the peri-pancreatic lymph nodes and derived from small (<1 cm in diameter) multiple duodenal gastrinomas; gastrin-positive lymph node metastases were excised in 42.9% of our 21 patients operated for gastrinoma." (PMID 37894286, 2023). "Subsequent investigations, including elevated gastrin levels and a somatostatin receptor scan, confirmed the diagnosis of gastrinoma." (PMID 37700944, 2023). "The great majority of metastases were from duodenal gastrinoma and positive to gastrin immunostaining." (PMID 37894286, 2023). "Intravenous Ca administrations are used for the diagnosis of gastrinoma in human patients, because the excess of Ca induces the release of huge amounts of gastrin by the tumor." (PMID 36496782, 2022). "In children, the gastrin-producing NENs (gastrinoma) and insulin-producing NENs (insulinoma) are the most common functional pancreatic NENs." (PMID 36291833, 2022). "In Zollinger-Ellison syndrome, a rare neuroendocrine tumour (gastrinoma) produces high levels of gastrin, leading to abnormally increased gastric acid production." (PMID 34671320, 2021). "Gastrinoma or otherwise known as Zollinger-Ellison syndrome is characterised by hypersecretion of gastrin and gastric acid leading to the formation of recurrent atypical ulcers along the upper gastrointestinal tract." (PMID 34447640, 2021). "Arguably the most serious of these is a gastrin-secreting tumour (gastrinoma) leading to the hypersecretion of gastric acid and the clinical manifestations of Zollinger-Ellison Syndrome (ZES)." (PMID 34867785, 2021). "Even though in normal subjects, secretin inhibits gastrin release, it stimulates the gastrinoma cells to release gastrin, which leads to a significant increase in serum gastrin levels." (PMID 34671320, 2021). "We therefore suggest that in case of symptoms suggestive of foregut NET (e.g., insulinoma or gastrinoma), the initial biochemical investigations should be restricted to the relevant specific hormone (e.g., insulin or gastrin)." (PMID 33138020, 2020). "In Case 3 gastrinoma, tumor cells were granular, less stained for gastrin but strongly stained for CgA and weakly for SPY." (PMID 32020844, 2020). "All patients with gastrinomas had elevated fasting serum gastrin level (mean, 636 pg/ml; SEM, 100 pg/ml; range, 404-14 000 pg/ml [to convert to picomoles per liter, multiply by 0.481])." (PMID 33146734, 2020). "In this test, glucagon is infused at 20 μg/kg/h for 30 min: Diagnosis of gastrinoma is likely when the percentage of increase over the baseline gastrin peaks within 10 min following glucagon administration, with circulating gastrin over 200 pg/mL." (PMID 31382663, 2019). "Measurement of fasting serum gastrin (FSG) is suggested to suspect the presence of a gastrinoma and to diagnose Zollinger–Ellison syndrome (ZES): high FSG (often over ten times the upper limit of normal) and low gastric pH is required to perform diagnosis." (PMID 31382663, 2019). "Soon thereafter, he presented with symptoms and elevated gastrin levels suggestive of ZES prompting abdominal exploration with partial resection of the duodenum to remove gastrinoma tumor nodules." (PMID 31818296, 2019). "Patients with MEN1 having gastrinomas were identified in the Dutch MEN1 database from 1990 to 2014 based on fasting serum gastrin (FSG) levels and/or pathology." (PMID 31401809, 2019).
gastrinoma (continued). "Surgical pathology showed metastatic neuroendocrine carcinoma, which was gastrin- and chromogranin-positive, compatible with metastatic gastrinoma in the lymph nodes and pancreas." (PMID 31818296, 2019). "Zollinger-Ellison syndrome (ZES) results from hypersecretion of gastrin producing gastrinoma tumors by which overproduction of gastric acid leads to severe peptic ulcer disease and the possible development of gastric carcinoid tumors." (PMID 31818296, 2019). "The diagnosis of gastrinoma is indicated by elevated fasting serum gastrin concentration (gastrin levels 10 times greater than the upper limit of normal) in the presence of hyperchloridria or gastric pH <2." (PMID 31263451, 2019). "Zollinger-Ellison syndrome (ZES) is a rare condition characterized by hypersecretion of gastrin by gastrinoma tumors leading to severe peptic ulcer disease with potential development of gastric carcinoid tumors." (PMID 31818296, 2019). "Later in 1993, he began to complain of diarrhea and was discovered to have elevated gastrin levels consistent with Zollinger-Ellison syndrome, prompting abdominal exploration with duodenectomy and resection of gastrinoma tumors." (PMID 31818296, 2019). "Multiple duodenal tumors and pancreatic head lesions were gastrin- and chromogranin-positive, consistent with gastrinoma." (PMID 31818296, 2019). "Measurement of serum gastrin has been suggested to be useful for the diagnosis of gastrinomas in dogs if increases in serum gastrin are in excess of three to ten times the upper limit of the reference interval (RI)." (PMID 29115998, 2017). "Serum gastrin concentrations >3× or >10× above the URL (the currently used criteria for the diagnosis of gastrinoma) were rare in all dogs with CE (acid-suppressant-treated: 8% and 4%, respectively; untreated: 4% and 1%, respectively) in this study." (PMID 29115998, 2017). "Although the use of historical controls is controversial, with canine gastrinoma it was deemed necessary in order to determine the sensitivity and specificity of the gastrin assay due to the very low prevalence of this neoplastic condition." (PMID 29115998, 2017). "This case of MEN1 with pancreaticoduodenal gastrinomas, accompanied with a high level of serum gastrin (≥3000 pg/mL, normal: ≤200 pg/mL), developed severe esophageal stenosis and complained of dysphagia, despite administration of full-dose PPI." (PMID 28270118, 2017). "Serial measurement of gastrin levels following intravenous administration of secretin can also be performed revealing an increase in gastrin levels for patients with gastrinoma, whereas they decrease in healthy individuals." (PMID 29257854, 2017). "Serum gastrin concentration can help diagnose gastrinomas in dogs if >3–10× the upper reference limit (URL), but antisecretory therapy and other conditions can also cause hypergastrinemia." (PMID 29115998, 2017). "In the 14 canine gastrinoma cases reported in the literature to date where serum gastrin was measured, the respective concentrations ranged from 72 to 2780 ng/L (median: 519 ng/L, IQR: 370–1020 ng/L; central 95th percentile: 90–2705 ng/L)." (PMID 29115998, 2017). "Gastrinomas are characterised by ectopic secretion of gastrin from pancreatic or duodenal NET, and resultant gastric ulcers." (PMID 28194228, 2017). "The diagnosis of gastrinoma can be confirmed with a secretin stimulation test, with an increase in circulating gastrin levels of >200 pg/ml above baseline after intravenous administration of 1–2 μg/kg of body weight of secretin." (PMID 25698559, 2015). "In patients with gastrinomas, high serum gastrin concentrations are responsible for acid hypersecretion, which induces ulcers in the stomach." (PMID 25698559, 2015). "If gastrin sensitivity is positive, removing the gastrin source by antrectomy (in type I) or gastrinoma resection (in type II) should result in tumor regression." (PMID 25698559, 2015).
gastrinoma (continued). "Zollinger-Ellison syndrome (ZES) is a syndrome characterized by hypersecretion of gastrin from gastrinomas—a type of neuroendocrine tumor—which can lead to refractory peptic ulcers in the upper gastro-intestinal tract." (PMID 25698559, 2015). "Gastrinomas originating from stomach had higher gastrin level and lower tumor grading and presented at older age." (PMID 26077245, 2015). "Gastrinoma is a functioning GEP-NEN, usually located in the duodenum or pancreas that secretes gastrin and causes a clinical syndrome known as ZES." (PMID 25038902, 2014). "Initially described in 1955, Zollinger–Ellison syndrome is characterized by multiple and recurrent peptic ulcers and persistent diarrhea that result from gastrin-secreting neuroendocrine tumors (gastrinomas) of the gastrointestinal tract." (PMID 23432909, 2013). "Pancreatic gastrin expression disappears after birth, but can reappear pathologically in the form of gastrin-secreting neuroendocrine tumors (gastrinomas), most of which are malignant." (PMID 23940571, 2013). "During adult life, gastrin can be re-expressed in the pancreas in the form of functional islet cell tumors, ∼40% of which are gastrinomas." (PMID 23940571, 2013). "Very little is known about the origins and the molecular determinants of pancreatic gastrinomas and fetal pancreatic gastrin expression." (PMID 23940571, 2013). "Forty-two percent (range 20%–61%) of the patients will develop a gastrin-secreting neuroendocrine tumour, a gastrinoma." (PMID 24213225, 2012). "The occurrence of gastrin cell hyperplasia at various sites in the duodenal mucosa explains the multifocality of gastrinomas in MEN-1." (PMID 24213225, 2012). "It has been demonstrated recently that gastrinomas associated with MEN-1 are preferentially located in the duodenum, arise from gastrin cell hyperplasia, so-called precursor lesions that develop to micro-tumours after loss of heterozygosity." (PMID 24213225, 2012). "Forty-two percent of the patients will develop a gastrin-secreting neuroendocrine tumour, a gastrinoma." (PMID 24213225, 2012). "An increase of gastrin >120 pg/dL after 2–5 min of secretin infusion is considered a suggestive result for gastrinoma; the response to secretin is relative to the presence of receptors for secretin on the gastrinoma cells." (PMID 24213321, 2012). "Markers of gastrinoma aggressiveness can be recognized in elevated fasting gastrin levels, poor tumoral differentiation, high mitotic number, Ki 67 positivity, and expression of progesterone receptors." (PMID 24213321, 2012). "Forty to 60% of gastrinoma patients in the fasting state had a gastrin concentration below 10 times normal and this overlaps with gastrin concentrations seen in Helicobacter pylori infection." (PMID 24213225, 2012). "Hypercalcaemia (due to hyperparathyroidism in MEN-1 patients, which predeces the manifestation of gastrinoma in most patients) has been shown to increase the serum gastrin concentration in fasting patients with Zollinger-Ellison syndrome." (PMID 24213225, 2012). "Zollinger-Ellison syndrome (ZES) is characterized by hypersecretion of gastrin from a gastrinoma that leads to gastric acid hypersecretion and, most notably, clinical symptoms of refractory peptic ulcer disease." (PMID 16042772, 2005). "In MEN1/ZES patients, duodenal gastrinomas have been shown to arise from the duodenal G cells by a process of progressive hyperplasia in a similar manner to that proposed for the response of ECL cells to gastrin in the stomach." (PMID 41463062, 2025). "In patients with gastrinoma, serum gastrin levels are generally 10 times above normal." (PMID 40291307, 2025). "Gastrinomas produce Zollinger-Ellison syndrome from excess gastrin which can lead to peptic ulcers." (PMID 40144450, 2025). "Gastrinoma is a rare neuroendocrine tumor characterized by the hypersecretion of gastrin." (PMID 40291307, 2025).